CD44 (CD44 molecule (IN blood group))
Diseases named in the same sentence as CD44 in open-access papers (continued):
Sharing a sentence is not in itself a finding about the gene and the disease.
ovarian carcinoma (continued). "The phenotype of CD44+/CD24− in ovarian cancer cells has been reported to exhibit CSC-like properties of enhanced differentiation, invasion, and resistance to chemotherapy, while CD44+/CD24+/Epcam+ exhibited stem cell characteristics in other reports." (PMID 30818864, 2019). "Our study has proposed a new mechanism by which CD44 induces the EMT progress via ZEB1 and Snail in ovarian cancer." (PMID 31497537, 2019). "There are different surface markers used to isolate ovarian cancer stem cells, including CD133+, CD133+/ALDH+, CD44+/MYD88+, CD44+/CD117+, CD44+/CD24+, and many others." (PMID 31366178, 2019). "In one prostate and two ovarian cancer cell lines, knock-down or inhibition of the mitochondrial pyruvate carrier (MPC) led to increased expression of Nanog, CD44, ALDH1, and HIF1α." (PMID 31661927, 2019). "To estimate the targeted effect of CSC vaccinations on the elimination of CSC subset, we analyzed the CD44+CD117+ cell and ALDH-positive cell subsets in ovarian cancer tissues from the CSC-vaccinated mice." (PMID 31008116, 2019). "In recent years, various specific markers of stemness, including CD44, CD117, aldehyde dehydrogenase (ALDH), CD133, CD24, and the epithelial cell adhesion molecule (EpCAM), have been used to isolate and characterize ovarian cancer stem cells." (PMID 31261739, 2019). "In the present study, we systematically evaluated the prognostic value of CD44 in ovarian cancer patients, and explored the modulation of CD44 on EMT in ovarian cancer cell lines." (PMID 31497537, 2019). "In the future, well-designed cohort studies with a larger sample size and more complete follow-up data, as well as in-depth molecular mechanism researches are needed to elucidate the role of CD44 and ZEB1 in the chemoresistance of ovarian cancer." (PMID 31497537, 2019). "In ovarian cancer, oHA disrupted the localization of ABCB1 with CD44 and inhibited drug efflux function." (PMID 30513961, 2018). "Among the CSC markers, CD44, EpCAM, c-Kit, CD133, Oct3/4 have been shown to be abundantly expressed in ovarian carcinomas, metastatic and recurrent tumors." (PMID 29682172, 2018). "Some of them, such as MUC4, CD44, L1CAM, ALCAM and P-cadherin, promote the malignant tendency of ovarian carcinoma cells." (PMID 30274262, 2018). "So far, no universal marker combination has been found to faithfully indicate ovarian cancer stem-like cells (CSLC), although surface proteins CD44 and CD133 are proposed by several authors (reviewed in:)." (PMID 30018258, 2018). "A biodegradable nanoparticle improved the delivery of CD44 and FAK siRNAs to ovarian cancer xenografts and reduces the tumor growth." (PMID 29747682, 2018). "CD117 (c-kit), CD44, CD24, and CD133 are usually expressed in solid tumors including ovarian cancer." (PMID 30581772, 2018). "In this study, CD44, EpCAM, c-Kit and CD133 were used as CSC markers to study the responses of paclitaxel and/or momelotinib treatments in in vitro ovarian cancer cell lines." (PMID 29682172, 2018). "STn is found on a number of proteins expressed on ovarian cancer cell surface including proteins such as MUC1 and CD44." (PMID 30052649, 2018). "Flow cytometry (FC) detection of CD44 and CD133 showed that the majority of ovarian cancer lines tested contained approximately 0.1% of CD44+/CD133+ cells (putative CSLC)." (PMID 30018258, 2018). "To this end, we downregulated VDR expression in the ovarian cancer cell line 2008, treated cells with calcitriol, and determined the CSC populations characterized by CD44+CD117+ or ALDH+." (PMID 29581858, 2018). "Various specific markers including ALDH1/2, CD133, CD117, CD24, CD34, CD44, CD133, EpCAM, LGR5 and LY6A have been employed for isolation and characterization of ovarian CSCs from ovarian cancer cell lines, patients’ tumors and ascites." (PMID 30121075, 2018).
ovarian carcinoma (continued). "Consistent with this study, we observed that glucose-restricted cells exhibit increased expression of ovarian cancer stem cell markers, such as CD117 (KIT and CD44, as well as decreased expression of CA125 (MUC16)." (PMID 28412735, 2017). "In ovarian cancer, the most common CSCs identified include CD24, CD34, CD44, CD117, ALDH1, EpCAM, SSEA4, NANOG, MYD88, and SOX2 positive cells." (PMID 29190952, 2017). "In our previous studies in vivo, we showed a significant increase in CSCs: CD24, CD34, CD44, CD117, ALDH1 and OCT4, in tumors collected from animals bearing orthotopic ovarian cancer followed by treatment with cisplatin." (PMID 29190952, 2017). "Both CD44 and CD117 were used as tumorigenic and stemness indicators in ovarian cancer cells, SKOV-3 cancer stem cells were confirmed by CD44+ (positive) and CD117+ (positive) selection." (PMID 29340100, 2017). "These ovarian cancer stem-like cells overexpressed specific ovarian cancer stem cell markers including CD24, CD44, CD117, CD133 and ALDH." (PMID 28459431, 2017). "TRX-E-002-1 was assessed against ovarian cancer stem cell line OCSC2, characterised by their expression of stem cell markers including CD44 and MyoD." (PMID 28013349, 2017). "In ovarian cancer cells SKOV3 and OVCAR3, originated from human ovarian cancer ascites cells, expression of either CD44, CD24 or CD133 markers is related to drug-resistance, a stem-like characteristics of cancer cells." (PMID 27655682, 2016). "Clinically, 80 to 90 % of ascites cancer cells from our ovarian cancer patients expressed CD 44, 5 to 15 % expressed CD133, and only 3 % expressed both CD44 and CD133." (PMID 27655682, 2016). "In 97 patients with ovarian cancer, MMP-14 and CD44 expression as determined by immunohistochemistry was investigated in relation to EMT-like changes." (PMID 27590006, 2016). "In the results from our ovarian cancer patients, among these markers, CD97, CD104, CD107a, and CD121a are significantly more expressed in the CD133 and CD44 double-positive ascites cells (Ascites_133+44+ cells) than in ovarian or metastatic tumors." (PMID 27655682, 2016). "And c-kit, along with Oct4, Nanog, SOX2, CD133, CD44, and ALDH1, has been considered as a cancer stem cell marker in primary non-small cell lung cancer (NSCLC), ovarian cancer and hepatocellular carcinoma." (PMID 26958807, 2016). "The expression of CD133+/CD44+, mostly expressed in the cancer stem-like cells, are similar in SKOV3 or OVCAR3 induced cells and the ascites cancer cells from ovarian cancer patients." (PMID 27655682, 2016). "The ascites tumor cells from human ovarian cancers demonstrated more CD133 and CD44 expressions than those from primary ovarian or metastatic tumors and confer tumorigenicity in immunodeficient mice." (PMID 27655682, 2016). "The ascites cells with high CD44 and CD133 expressions, from ovarian cancer patients, displays more potentials for self-renewal and long-term proliferation." (PMID 27655682, 2016). "From this cohort study on MMP-14 and CD44 expression in ovarian cancer, we conclude that the subgroup of patients with positive expression of both MMP-14 and CD44 had type-I tumors with poor prognosis despite complete debulking." (PMID 27590006, 2016). "Ovarian Cancer Stem Cell biomarkers (CD133 and CD44) also showed increased expression with increasing resistance." (PMID 27819360, 2016). "Previous studies have investigated the expression of the three molecules individually in malignant ovarian tumors and have found that CD44 and c-met are highly expressed in OCCC, while CD47 is highly expressed in ovarian cancer tissues." (PMID 25658794, 2015). "In the current study, we studied the efficiency of siRNA delivery of MDR1 siRNA loaded HA-PEI/HA-PEG CD44 targeted nanoparticles and their effects on circumventing drug resistance in an MDR ovarian cancer model in vitro and in vivo." (PMID 25687880, 2015).
ovarian carcinoma (continued). "To assess the targeted effect of the CSC vaccine on elimination of CD44+CD117+CSCs, we investigated the CD44+CD117+double positive cell population in ovarian cancer tissues from the vaccinated mice." (PMID 26497895, 2015). "Finally, there is a hypothesis that CD44 function varies during different stages of tumor growth, from initiation to formation of metastases, which has yet to be explored in the context of epithelial ovarian cancer." (PMID 26569327, 2015). "As MDR1 is the major mechanism for paclitaxel resistance, the combination of MDR1 siRNA CD44 targeted nanoparticle and paclitaxel hold great potential to increase paclitaxel sensitivity/efficacy and overcome MDR in ovarian cancer treatment." (PMID 25687880, 2015). "With the intent to isolate CSC ovarian cancer, 37 primary tumor samples were evaluated for the expression of CXCR4/CD133 and CD44/CD24." (PMID 26020117, 2015). "It is thus evident from these results that the administration of the CD117+CD44+CSC vaccine to mice led to disease of the CD44+ CD117+CSC and ALDH-positive cell populations in ovarian cancer tiuuses from immunized mice." (PMID 26497895, 2015). "Although the non-CD117+CD44+CSC and the SKOV3 cell vaccines showed marked efficacy against ovarian cancer as well, this efficacy was actually more efficient in the mice immunized with the CD117+CD44+CSC vaccine." (PMID 26497895, 2015). "Binding of the CD44 with its ligand (HA) stimulates the kinase activity of HER-2/neu and leads to increased proliferation of cancer cells in many tumors, including ovarian cancer." (PMID 25129125, 2015). "In order to determine the underlying mechanism of how chemosensitivity to paclitaxel increased in the xenograft MDR ovarian cancer model in mice, the proteins of SKOV-3TR tumor mass were extracted to further determine the expression levels of Pgp and CD44." (PMID 25687880, 2015). "ONCOFID-P was subsequently evaluated for i.p. treatment of ovarian cancer against CD44 + OVCAR-3 and SKOV-3 human ovarian cancer cell lines, xenografted in nude mice." (PMID 24642908, 2014). "AuNPs inhibit cisplatin induced EMT, decrease the side population cells and key stem cell markers such as ALDH1, CD44, CD133, Sox2, MDR1 and ABCG2 in ovarian cancer cells." (PMID 25071019, 2014). "c-kit has been regarded as a cancer stem cell marker as Oct4, Nanog, SOX2, CD133, CD44, ALDH1, Gata-4, Isl-1, and nestin in primary non small cell lung cancer, ovarian cancer and hepatocellular carcinoma." (PMID 24721839, 2014). "In an ovarian cancer study, ALDHBr cells were more enriched in CD44+ cells than in use of the CD133+ cells, but the ALDHBr and CD44+ overlapping was partial." (PMID 23967051, 2013). "In another study, CD44 and CD133 expression was increased through the Sox2 and OCT3/4 regulation in two different ovarian cancer cell lines (ES-2 and OVCAR3)." (PMID 23484135, 2013). "In this context, few previous studies have demonstrated the existence of CSC-enriched side population of cells or CD44, CD117, CD133, CD24 enriched population of cells in ovarian cancer cell lines or ovarian cancer patient’s samples." (PMID 23537295, 2013). "Several cell surface antigens such as CD44, CD117, CD133 and MYD88 have been used to isolate ovarian cancer stem cells." (PMID 23782518, 2013). "The co-localization of CD44 with ABCB1 and ABCC2 in ovarian cancer tissues suggests a functional link between CD44 expression and chemoresistance." (PMID 24124770, 2013). "Recent reports have identified CD44 as a potential marker for the identification of cancer stem cells in ovarian cancer, and confirmed the functionality of the TLR4-MyD88 pathway in only the CD44+ cell population." (PMID 22533866, 2012). "Apart from CD44, many studies refer CD24 with vital role in ovarian cancer metastasis, and it can be used as a potential CSC marker." (PMID 22693526, 2012).
ovarian carcinoma (continued). "With critical review of literature, it appears that the importance of CD44 and CD24 expression in ovarian cancer is more debatable." (PMID 22693526, 2012). "Studies in ovarian cancer stem cells showed that the two subtypes of epithelial ovarian cancer (EOC) stem cells, type I/CD44+ and type II/CD44-, have a very distinct expression pattern of miR-199a, with type II levels being much higher." (PMID 22942713, 2012). "Some of the most commonly identified markers are CD133, CD44, and CD24, which are found in breast, prostate, pancreas, and ovarian cancer." (PMID 21904548, 2011). "Aldehyde dehydrogenase (ALDH1) has been proven useful for the identification of cancer stem cells, including ovarian cancer; therefore, we evaluated the expression of ALDH1 in the identified CD44+ EOC stem cell clones." (PMID 21904548, 2011). "Similarly, compared with normal tissues, CD44 and FTH1 expression were significantly downregulated in advanced-stage (FIGO III/IV) and high-grade (G3) ovarian cancer tissues." (PMID 41210681, 2025). "The results revealed that selected thioaptamers (monothiophosphate-modified) aptamers bound to CD44-positive human ovarian cancer cell lines but failed to bind to the CD44-negative cell line." (PMID 41440277, 2025). "Since CD44 is highly expressed in EOC, and is the cognate receptor for HA, we sought to enhance the delivery of TCS2210 and selectively deliver this compound to ovarian cancer cells by incorporating a CD44 targeting peptide within the nanoparticle." (PMID 38796478, 2024). "Moreover, inhibition of autophagy through ATG5 knockdown resulted in a decrease in the CD44 + CD117+ cell proportion, concurrently diminishing both the chemoresistance and tumorigenic potential of ovarian cancer stem cells." (PMID 39272847, 2024). "Established primary cultures were stained for ovarian cancer markers CA125, EpCam, and CD44." (PMID 38898005, 2024). "Moreover, NRF2 and its target genes were highly expressed in CD44+/CD24− breast cancer cells, ALDH+ ovarian cancer cells, and CD133+ colon cancer cells." (PMID 38704599, 2024). "The authors demonstrated that silencing FAK and CD44 with shRNA led to significant inhibition of the growth of human ovarian cancer xenografts in nude mice without systemic toxicity, highlighting the safety of PLGANPs." (PMID 39125873, 2024). "Furthermore, flow cytometry was used to quantify cells positive for CD44, CD117, CD133, and aldehyde dehydrogenase (ALDH) activity, all markers of stemness that have been validated in ovarian cancer." (PMID 38612653, 2024). "According to the analysis, the expression of CD133 and CD44 had no statistically significant impact on the overall and progression-free survival in patients with epithelial ovarian cancer." (PMID 36768723, 2023). "In addition, osteopontin released by cancer-associated mesothelial cells has been shown to induce chemoresistance via activation of CD44, PI3K-AKT signaling, and ABC drug transporter in ovarian cancer cells in vitro." (PMID 37545408, 2023). "Moreover, in contrast to ALDH1 and CD44, CD133 was suggested to be a marker of recurrent ovarian cancer." (PMID 38201468, 2023). "Interestingly, AhRR and PPP1R3C expression significantly correlates with stemness markers’ (ALDH1A1, CD44, ABCG2, NANOG) expressions in ovarian cancer tissues (p < 0.01)." (PMID 37511212, 2023). "Overexpression of CD44 and its isoforms promotes tumor growth, cell migration, and metastasis, through its participation in the epithelial–mesenchymal transition process (EMT), in a range of neoplasms, including ovarian cancer." (PMID 36768723, 2023). "Switching from CD44 variant isoforms containing exon v7 to isoform 4 without change in a total amount of CD44 was observed in human epithelial ovarian cancer cell line HO8910 with a stable suppression of ESRP1 expression." (PMID 38106992, 2023).
ovarian carcinoma (continued). "The results of an analysis of EMT markers and cell morphology showed that epithelial ovarian cancer (EOC)-derived EVs promoted the EMT independent of TGFβ signalling by transferring CD44+ EVs to human peritoneal mesothelial cells (HPMCs)." (PMID 37735659, 2023). "These targeted albumin NPs were more cytotoxic to ovarian cancer cells overexpressing CD44 (SKOV3 cells) than free PTX, but not to cells with low expression of CD44, which provides evidence for a CD44-mediated uptake of the PTX-loaded NPs." (PMID 35203695, 2022). "In order to scrutinize the initiating cell status and identity of iOVCAR-3-OSKM cells, we evaluated the expression levels of several ovarian cancer initiating cell (OCIC) markers that previously reported like CD133, CD177, CD24, CD44, ABCG2, and ALDH1 in cells." (PMID 36085021, 2022). "CD44+/CD24–/low cells have been described as breast and prostate cancer stem cells; stem-like properties, including increased proliferation, angiogenesis, and resistance to chemotherapy, have been attributed to CD44+/CD24–/low NSCLC, and ovarian cancer cells as well." (PMID 36013184, 2022). "We only use CD44/CD117 as markers of ovarian cancer stem cells in this study, lack of research on the expression of CD133 and ALDH." (PMID 36046821, 2022). "MicroRNA-199a could target CD44, restore chemosensitivity to paclitaxel, cisplatin, and adriamycin, and reduce ABCG2 expression, a multidrug resistance gene in in vitro and in vivo ovarian cancer models." (PMID 35464064, 2022). "At the molecular level, we evaluated basal expression levels of the HA axis in a panel of ovarian cancer cell lines and compared control ovarian cancer cells and HAS2 knockdown cells regarding gene expression of HAS1-3 and HYAL2-3, CD44, RHAMM and versican by qPCR." (PMID 35767191, 2022). "Because of the more reasonable proportion of positive cells in 5 EOC cell lines than in other common CSC biomarkers, such as CD44, CD117 and CD133, CDC50A might be a candidate biomarker of epithelial ovarian cancer-initiating cells." (PMID 35982417, 2022). "Also worthy of further clinical exploration are expression levels of CD44, ALDH1, p-FAK/FAK, and p-YB1/YB1, as well as CSCs and other potential predictors and/or pharmacodynamic biomarkers, in ovarian cancer." (PMID 35820889, 2022). "Cells sorted for positive CSC markers such as CD44+/CD117+ and CD133+ were designated as stem-like cells of ovarian cancer (ovarian cancer stem cells; OCSC) and were found to have a higher ability to form spheres and higher tumorigenesis compared to cells without CSC markers." (PMID 36077833, 2022). "Importantly, in mice transplanted with chemoresistant CD44+ ovarian cancer stem cell xenografts, multiple intraperitoneal treatments with sublethal doses of CPE significantly inhibited ovarian cancer progression." (PMID 36437919, 2022). "A number of markers expressed on ovarian cancer stem cells have been described in the literature: CD133 (prominin), ALDH (aldehyde dehydrogenase), CD44 (hyaluronan), CD117 (c-kit), MyD88 (myeloid differentiation primary response protein), CD24 (mucin-like adhesion molecule)." (PMID 34440558, 2021). "Despite the function of CD44 as a stem cell biomarker, contradictory findings suggest that CD44 fails to function as a prognostic factor in ovarian cancer." (PMID 34064635, 2021). "CD44 is involved in oocyte maturation in mammals and expressed in ovarian cancer stem cells, but a role for CD44 in fish gonads has not been explored to our knowledge." (PMID 34020589, 2021). "Although current evidences show that various biological markers could predict the prognosis of ovarian cancer, such as CA125, HE4, CD24, CD44, CD133, SSEA and so on, few targets reported are related to tumor metabolism." (PMID 33403023, 2021).